SIRT3 (sirtuin 3)
Diseases named in the same sentence as SIRT3 in open-access papers (continued):
Sharing a sentence is not in itself a finding about the gene and the disease.
Parkinson disease (29 papers, 2012 to 2025). A progressive degenerative disorder of the central nervous system characterized by loss of dopamine producing neurons in the substantia nigra and the presence of Lewy bodies in the substantia nigra and locus coeruleus. "Age-related declines in SIRT3 activity have been linked to neurodegenerative diseases, such as Alzheimer’s and Parkinson’s, where mitochondrial dysfunction and oxidative damage are hallmarks." (PMID 40799515, 2025). "Alterations in locomotor activity have been linked to changes in mitochondrial number, Ca2+ levels, and proteome acetylation, and elevating Sirt3 expression has also been associated with motor function improvement in a model of Parkinson’s Disease." (PMID 36148309, 2022). "ε-Viniferin had an anti-inflammatory effect via the targeting of formyl peptide receptor 1 in human neutrophils, and Sirtuin 3 (SIRT3)-mediated neuroprotective effects in Huntington’s disease models and Parkinson’s disease models caused by rotenone administration of SH-SY5Y cells." (PMID 40141054, 2025). "We developed clinically scalable, microbubble drug conjugates (MDCs) for the viral gene therapy, AAV.SIRT3-myc [adeno-associated virus expressing myc-tagged SIRT3], which has previously been shown to have disease modifying effects in animal models of Parkinson’s disease (PD)." (PMID 35393905, 2022). "Overexpression of SIRT3 exhibited a protective role in rotenone-induced Parkinson's disease cell model by activating AMPK/mTOR pathway." (PMID 35291946, 2022). "Presumably this role for SIRT3 extends to other neurodegenerative diseases where mitochondrial oxidative stress is a key component of neuronal decline, including Parkinson’s disease and multiple sclerosis." (PMID 23139766, 2012). "In Parkinson's disease, SIRT3 plays a positive neuroprotective role." (PMID 40259181, 2025). "In addition, mitochondrial activation by Sirt3 was neuroprotective in a cell model of Parkinson’s disease." (PMID 39457098, 2024). "Thus, SIRT3 plays a very important role in regulating neurodegeneration in diseases such as Alzheimer’s and Parkinson’s disease." (PMID 34830158, 2021). "We previously reported the protective effect of SIRT3 on a Parkinson’s Disease cell model." (PMID 29896416, 2018). "SIRT3 activators that could improve Parkinson’s disease found in nearly a decade." (PMID 40969935, 2025). "SIRT3, via the activation of FOXO3, leads to induction clustering of p62—also a common component of Lewy bodies in Parkinson’s disease —on ubiquitinated mitochondrial substrates, alleviating AD-associated toxicity." (PMID 34830158, 2021). "These have not been analysed previously in the context of Parkinson’s disease pathogenesis, in contrast to other sirtuin family members (Sirt1, Sirt2, and Sirt3)." (PMID 27763519, 2016).
Cognitive impairment (28 papers, 2017 to 2025). Abnormal cognition is characterized by deficits in thinking, reasoning, or remembering. "Dexmetomidine alleviates hippocampal damage and cognitive impairment caused by liver ischemia/reperfusion in young rats by activating SIRT3-mediated mitophagy and inhibiting the activation of NLRP3 inflammasomes." (PMID 38012584, 2023). "To further explore the mechanism of cognitive impairment caused by neuronal injury through SIRT3 signaling, we also performed a series of in vitro experiments." (PMID 37210391, 2023). "Our study of the effects of NAM were examined in vitro and in an animal model, not clinically, so further clinical investigations of the therapeutic potential of NAD+/SIRT3 on cognitive impairment associated with schizophrenia are now required." (PMID 37210391, 2023). "In old mice with cognitive impairments, loss of function of both SIRT3 and MnSOD has been found in hippocampal cells." (PMID 36045741, 2022). "And the regulation of the NLRP3/BDNF/SIRT3 axis could reduce inflammation and oxidative stress during seizures, improving cognitive impairment caused by seizure." (PMID 40969935, 2025). "Additionally, treating normal rats with 3-TYP (a SIRT3 inhibitor) caused cognitive impairment and increased neuronal apoptosis in the hippocampus and PFC." (PMID 37210391, 2023). "Our results showed that anesthesia and surgery induced cognitive impairment in mice and reduced sirtuin 3 protein expression." (PMID 40145974, 2025). "Overexpression of sirtuin 3 inhibited opening of the mitochondrial permeability transition pore by reducing acetylation of K166 on cyclophilin D and also rescued cognitive impairment." (PMID 40145974, 2025). "DL-3-n-butylphthalide improved learning and cognitive impairment in VD mice by inhibiting the Nrf2/SIRT3 pathway, which reduced autophagy and apoptosis." (PMID 40969935, 2025). "Recently, a study has reported that HKL can mitigate cognitive deficits in mice with AD by activating SIRT3 and improving mitochondrial function in the neurons." (PMID 39097923, 2024). "Nicotinamide riboside, a SIRT3 agonist, protects transgenic mouse models of AD against cognitive impairment, synaptic degeneration, and neuronal death." (PMID 36918872, 2023). "Further, up-regulating SIRT3 alleviated hippocampus injuries and cognitive impairment in diabetic mice and mitigated mitochondrial Ca2+ overload-induced mitochondrial dysfunction and apoptosis." (PMID 37481555, 2023). "In this study, we investigated the role of SIRT3 in hippocampal injuries and cognitive impairment in diabetic mice and cell injuries in HG-induced SH-SY5Y cells." (PMID 37481555, 2023). "SIRT3 overexpression rescued hippocampus injuries and cognitive impairment in diabetic mice by alleviating mitochondrial dysfunction and apoptosis." (PMID 37481555, 2023). "It is worth noting that EPA demonstrated an advantage in reducing seizure-induced cognitive impairment by inhibiting ferroptosis, with a stronger enhancement of Sirt3 observed in the PTZ-kindling young mice model." (PMID 37755077, 2023). "In summary, our findings suggest that SIRT3 ameliorates cognitive impairment in diabetic mice by limiting aberrant MAM formation." (PMID 37481555, 2023). "In an animal model of AD, HMGB1 induced cognitive impairment through the Sirtuin 3/superoxide dismutase 2 signaling pathway." (PMID 36906561, 2023). "Treatment with HNK (a SIRT3 activator) similarly relieved the cognitive deficits and neuronal apoptosis induced by MS, while 3-TYP (a SIRT3 inhibitor) induced neuronal apoptosis and cognitive deficits in control and NAM-treated adult MS rats." (PMID 37210391, 2023). "The depletion of Sirt3 in mice showed cognitive impairments during the probe trial in the Morris water maze test." (PMID 38011257, 2023).
Cognitive impairment (continued). "Since SIRT3 can be post-translationally modified through phosphorylation or S-sulfhydration, further study is needed to ascertain how CCH-induced post-translational modification of SIRT3 is related to cognitive impairment." (PMID 33519419, 2020). "The results revealed that Dex treatment effectively attenuated neuroinflammation and cognitive deficits via upregulating SIRT3 expression and activity." (PMID 34493950, 2020). "Increasing SIRT3 and decreasing CypD can attenuate cognitive impairment and neuroapoptosis, and protect the integrity of mitochondrial membrane from damage and restore the protein expressions of IL-6, TNF-α, and caspase-3." (PMID 28236057, 2017). "Since SIRT3 is a deacetylase, its involvement in CypD-dependent modulation of mPTP opening during cognitive impairment was examined in this study." (PMID 28236057, 2017). "Modulating SIRT3-related signaling pathways has been shown to alleviate oxidative stress and mitochondrial dysfunction, improve neuronal/synaptic injury, and ameliorate cognitive impairment." (PMID 39091611, 2024). "This suggested that HKL might alleviate cognitive impairment and Aβ1–42 plaque deposition in AD mice by activating hippocampal mitochondrial autophagy via increasing SIRT3 expression." (PMID 39097923, 2024). "Here we investigated whether nicotinamide (NAM) normalized cognitive impairment via a mechanism involving the mitochondrial Sirtuin 3 (SIRT3) pathway." (PMID 37210391, 2023). "PACAP treatment attenuated cognitive disorder through autophagy in a Sirt3-dependent manner." (PMID 37891608, 2023). "Furthermore, SIRT3 overexpression protected against hippocampal injuries and cognitive impairment in diabetic mice." (PMID 37481555, 2023). "SIRT3 also protects mice from cognitive deficits induced by surgery/anesthesia brain injury." (PMID 36045741, 2022). "Consequently, the aim of our current study was to determine the effect of SIRT3 on anesthesia/surgery-induced cognitive impairment and the related molecular mechanism." (PMID 33541361, 2021). "Therefore, the aim of this study was to evaluate the effect of SIRT3 on anesthesia/surgery-induced cognitive impairment in aged mice." (PMID 33541361, 2021). "Thus, CTFE is suggested to have a neuroprotective effect on SCO-induced cognitive impairment by regulating autophagy in neuroinflammation through SIRT3-AMPK/ERK1/2-CREB signaling pathways." (PMID 33276674, 2020). "The results indicated that CypD increased in the SAE mice, and the function of cognitive impairment might have improved when SIRT3 was inhibited (P < 0.05)." (PMID 28236057, 2017). "Up-regulating SIRT3 may play a role of anti-oxidative stress, anti-mitochondrial dysfunction, and anti-neuroinflammation, relieving the hippocampal neurons apoptosis and improving cognitive impairment." (PMID 36918872, 2023). "However, we did not explore whether it can inhibit microglial inflammation and improve cognitive impairment in model animals by regulating Sirt3 expression." (PMID 36131290, 2022). "However, the effects of SIRT3-mediated deacetylation of CypD in cognitive impairment induced by SAE remain unknown." (PMID 28236057, 2017). "Some studies have shown that enhancing the expression or activity of SIRT3 can improve mitophagy in APP/PS1 transgenic mice, alleviating synaptic damage and cognitive deficits." (PMID 40125832, 2025). "In a study on AD mice, activation of the SIRT3 signaling pathway inhibited acetylation of HMGB1 induced by Aβ25-35, thereby restoring redox balance and inhibiting neuroinflammation, rescuing cognitive impairment in AD." (PMID 39091611, 2024).
glioma (28 papers, 2015 to 2026). A benign or malignant brain and spinal cord tumor that arises from glial cells (astrocytes, oligodendrocytes, ependymal cells). "Suppressing SIRT3 heightened mitochondrial damage, as shown by greater loss of membrane potential and increased ROS levels under hypoxia, and sensitized glioma cells to hypoxia-induced apoptosis." (PMID 40710366, 2025). "Overall, linalool’s inhibitory effects on glioma cell viability are linked to the downregulation of SIRT3, which in turn affects SOD2 activity and increases ROS levels." (PMID 40710366, 2025). "The genetic changes of SIRT genes in gliomas were explored, and the highest mutation rate occurred in SIRT3 with 1.9%, and the main form of mutation form was deletion." (PMID 36568393, 2022). "The deactivation of SIRT3 led to metabolic alterations, loss of stemness, and suppression of tumor formation in glioma stem cells in vivo." (PMID 34770867, 2021). "Inactivation of SIRT3 leads to metabolic alterations, loss of stemness, and suppression of tumor formation by glioma stem cells in vivo." (PMID 32117717, 2020). "ROC (Receiver-operating characteristic) curve analysis suggests that SIRT3 has good diagnostic sensitivity in glioma patients, suggesting it could be a valuable biomarker for diagnosis and prognosis." (PMID 40710366, 2025). "Indeed, we also found decreased levels of SIRT3 in overloaded muscle compared to control, and SIRT3 is implicated in mitophagy, since, in human glioma cells, silencing of SIRT3 blunted the degradation of mitochondria." (PMID 34299206, 2021). "Similarly, SIRT3 was found to be associated with oral squamous cell carcinomas (OSCCs) and glioma." (PMID 30538800, 2018). "In laboratory experiments, SIRT3 overexpression increased cell viability, while silencing SIRT3 reduced cell growth, indicating SIRT3 promotes glioma cell survival." (PMID 40710366, 2025). "The conclusion drawn from the study is that SIRT3 not only serves as a potential biomarker for glioma prognosis but also plays a significant role in glioma progression through its interaction with Ku70." (PMID 40710366, 2025). "ROC curve analysis was performed and >80 percent diagnostic sensitivity was measured in case of SIRT3 and SIRT5 genes in glioma patients." (PMID 36809279, 2023). "Sirt3-mediated deacetylation of Ku70 in human glioma cells stabilized the Ku70/Bax interaction and made cells more resistant to Bax-mediated apoptosis." (PMID 35938164, 2022). "Further investigation revealed that SIRT3 overexpression downregulated glioma cell apoptosis via the Ku70–BAX pathway." (PMID 36361680, 2022). "In human glioma cells, Sirt3 activated hypoxia-induced mitophagy by increasing the interaction of VDAC1 with Parkin." (PMID 35938164, 2022). "Sirtuin-3 (SIRT3) is a deacetylase that regulates mitochondrial metabolic homeostasis to maintain stemness in glioma stem cells." (PMID 35723384, 2021). "In glioma stem cells, SIRT3 was reported to regulate glioma CSCs with metabolic plasticity and maintain cancer stemness." (PMID 35723384, 2021). "Inhibition of either TRAP1 or SIRT3 in glioma stem cells leads to metabolic dysregulation, overproduction of ROS, loss of stemness properties, and cell death both in vitro and in vivo." (PMID 31947673, 2020). "In a glioma cell line, in vitro overexpression of SIRT3 was protective against apoptosis and significant progression of cell cycle towards G2/M." (PMID 30538800, 2018). "SIRT3 overexpression also drastically modifies the methylation profile of a glioma-derived cell line, with the hypermethylation of numerous genes at CpG islands." (PMID 30538800, 2018). "We observed that the protein levels of Mcl-1 and survivin were further decreased when Sirt3 expression was knocked down in glioma cells subjected to hypoxia." (PMID 27270321, 2016). "We further found that Sirt3 was involved in the activation of autophagy induced by hypoxia in human glioma cells." (PMID 27270321, 2016).
glioma (continued). "We found that silencing of Sirt3 expression in human glioma cells by RNA interference blunted the hypoxia-induced the localization of LC3 on the mitochondria, and the degradation of mitochondria." (PMID 27270321, 2016). "However, higher levels of SIRT3 are significantly associated with advanced tumor grades and shorter overall survival times in glioma patients, suggesting SIRT3 as an independent prognostic factor." (PMID 40710366, 2025). "For example, SIRT3 can promote the survival and invasion of glioma by inhibiting OS." (PMID 36374406, 2023). "In addition, the Kaplan–Meier curve showed that SIRT1, SIRT3, and SIRT5 were closely associated with OS, DSS, and PFI of glioma patients, and other SIRT family members are related to the prognosis of glioma patients to varying degrees." (PMID 36568393, 2022). "Another study noted that Sirt3 reduces ROS production in mitochondria within glioma stem cells." (PMID 34770867, 2021). "Since active scavenging of ROS is associated with glioma stem cell resistance to radiation and chemotherapy, the interplay between TRAP1 and SIRT3 may contribute to the therapeutic resistance of cancer stem cells in vivo." (PMID 31947673, 2020). "Furthermore, it has been recently proposed that TRAP1 is acetylated upon interaction with sirtuin-3 in mitochondria of glioma cells." (PMID 31878280, 2019). "Furthermore, we found that suppression of Sirt3 substantially increased the sensitivity of glioma cells to hypoxia." (PMID 27270321, 2016). "Notably, a recent study using glioma and renal epithelial tumor cells showed that mitochondrial OGG1 is a direct SIRT3 deacetylation target and that SIRT3 deficiency reduces the oxygen consumption rate (OCR) and 8OHdG mtDNA BER that increases mtDNA damage and intrinsic apoptosis." (PMID 26370974, 2015). "SIRT1, SIRT3, SIRT5, and SIRT7 are often overexpressed and promote glioma cell proliferation, stemness, therapy resistance, and metabolic adaptation." (PMID 40710366, 2025). "Furthermore, SIRT3 overexpression inhibits linalool-induced apoptotic cell death and the decrease in cell viability, highlighting its importance in maintaining cell survival, suggesting SIRT3 could be a potential therapeutic target against glioma." (PMID 40710366, 2025). "Gliomas, on the other hand, exhibit a biological response to Ex-4 through the GLP-1-R/Sirtuin 3 (SIRT3) signaling pathway, impeding proliferation, survival, and migration." (PMID 38672620, 2024). "Thus, the current study is designed to investigate expression level of SIRT3, SIRT4, SIRT5 and associated genes SOD1, SOD2, OGG1-2α, PARP1, GDH and HIF1α in glioma patients and to find out whether this expressional deregulation effects the risk of glioma." (PMID 36809279, 2023). "An interaction between TRAP1 and SIRT3 has been reported in glioma stem cells (GSC), where the two proteins reciprocally sustain their activities: SIRT3-mediated deacetylation maintains TRAP1 chaperone activity, which in turn stabilizes SIRT3." (PMID 35959462, 2022). "TRAP1 directly stabilizes one such deacetylase, sirtuin-3 (SIRT3), and augments SIRT3 activity in vitro and in glioma cells." (PMID 35740911, 2022). "In glioma stem cells, cooperative interplay between the mitochondrial chaperone TRAP1 and SIRT3 increases mitochondrial respiratory capacity and reduces the production of ROS." (PMID 32117717, 2020). "Very recently, it has been shown that SIRT3 and TRAP1 are overexpressed in glioma stem cells, and that the interplay between them increases activity of the ETC without increasing the ROS concentration in glioma stem cells mitochondria." (PMID 31947673, 2020). "Unlike SIRT3, which is upregulated in glioma patients, SIRT5’s downregulation highlights the different roles that these sirtuins play in cancer biology." (PMID 40710366, 2025).
glioma (continued). "In hypoxic glioma cells, SIRT3 promoted mitophagy, evidenced by the co-localization of GFP-LC3 with mitochondria and the reduction of mitochondrial mass—effects diminished when Sirt3 was inhibited." (PMID 40710366, 2025). "Present study was purposed to figure out the expression level of mitochondrial sirtuins (SIRT3, SIRT4, SIRT5) and related genes (GDH, OGG1-2α, SOD1, SOD2, HIF1α and PARP1) in 153 glioma tissue samples and 200 brain tissue samples from epilepsy patients (taken as controls)." (PMID 36809279, 2023). "In case of SIRT3 (p = 0.0142) and HIF1α (p = 0.0385) significant upregulation was observed while non-significant upregulated expression was observed in PARP1 (p = 0.203) in glioma samples as compared to healthy samples." (PMID 36809279, 2023). "Unlike SIRT4, which is downregulated in glioma patients, SIRT3’s upregulation indicates that different sirtuins may have distinct roles in glioma progression." (PMID 40710366, 2025). "Moreover, SIRT3 induces deacetylation of glycine decarboxylase (GLDC) and promotes glycine catabolism and pyrimidine synthesis, which is crucial for the proliferation of human glioma cells." (PMID 38773972, 2024). "SIRT3 expression was significantlydecreased in the aggressive GL tumors but the decrease was not significant ingrade II and III gliomas." (PMID 25791281, 2015). "The roles of SIRT1, SIRT2, SIRT3, and SIRT7 in glioma are not comprehensively understood." (PMID 36568393, 2022).